CD47 (CD47 molecule)
Diseases named in the same sentence as CD47 in open-access papers (continued):
Sharing a sentence is not in itself a finding about the gene and the disease.
tumor (continued). "Considering its ubiquitous expression, CD47 plays a central role in the tumor microenvironment (TME)." (PMID 32677994, 2020). "CAR-T cells can be engineered to express CD47-blocking antibodies in order to prevent that interaction, thus stimulating phagocytosis of tumor cells and improving engagement of the innate immune system." (PMID 32625204, 2020). "Antibodies blocking the interaction between CD47 on tumor cells and SIRPα on macrophages enhance macrophage phagocytosis, show efficacy in preclinical tumor models, and are being evaluated in the clinic." (PMID 33133093, 2020). "CD47-Sirpα—CD47 is a transmembrane protein expressed on the surface of many cells including tumor cells and helps in the survival of these cells." (PMID 33374595, 2020). "The inhibitory receptor signal regulatory protein-α (Sirpα) is a myeloid-specific immune checkpoint that engages the “don’t eat me” signal CD47, which is expressed on tumor and normal tissue cells." (PMID 32296015, 2020). "A study indicated that the accumulation of Bifidobacterium in TME can significantly improve the anti-tumor effect of anti-CD47 immunotherapy, which depends on the STING signal and the type I IFN within DC." (PMID 33488618, 2020). "CD47 on tumor cells can ligate with SIRPα on phagocytic cells, inhibiting their phagocytic capacity." (PMID 32331242, 2020). "Considering the potential of CD47-SIRPα signaling in regulation of DC function, we analyzed the changes in SIRPα+ DCs following tumor cell vaccination." (PMID 31996683, 2020). "In particular, given that synergistic action of Sirpα/CD47 blockade and ICBs has been reported in other tumor types, neutralization of Sirpα represents an attractive approach to increase the responsiveness of CRC patients to ICB." (PMID 32962159, 2020). "B6H12, an anti-human CD47 mAb, has been widely used to evaluate phagocytosis and anti-tumor activities induced by blocking CD47-SIRPα interaction." (PMID 31931812, 2020). "Another study showed that the signal-regulatory protein alpha (SIRPα) modified exosomes for blocking the “don’t eat me” signal via targeting CD47 on tumor cells." (PMID 33374978, 2020). "First, direct inhibition of CD47 or SIRPα promotes phagocytosis of tumor cells by disrupting the “don't eat me” signal provided by CD47, allowing the engulfment of tumor cells by macrophages." (PMID 33015199, 2020). "Control cells were treated with ETL NPs that bear a limited amount of CD47 on the surface, or free CD47 protein, which is known to enhance phagocytosis of tumor cells, or PBS." (PMID 32999828, 2020). "In a limited number of human malignancies, anti-CD47 therapy leads to the rapid clearance of tumor cells by macrophages." (PMID 32811852, 2020). "More importantly, our co-IP and mass spectrometry data revealed that ENO1 was a downstream target of CD47 in the tumor cells." (PMID 32226539, 2020). "Blockade of CD47-SIRPα interaction increases macrophage-mediated phagocytosis and enhances tumor elimination in a variety of preclinical models." (PMID 31931812, 2020). "The CD47 expression in different tumor tissues from The Cancer Genome Atlas (TCGA) and Genotype-Tissue Expression (GTEx) data sets was evaluated." (PMID 33020240, 2020). "An anti-CD47 antibody would presumably increase tumor cell phagocytosis and antitumor CD8+ T cell response priming." (PMID 32811852, 2020). "CD47 expressed by tumor cells binds to signal regulatory protein α (SIRPα) on TAMs suppressing tumor cell phagocytosis." (PMID 32326073, 2020). "A growing evidence that the blockade of CD47-SIRPα interaction “don’t eat me” signal enhances the activity of phagocytes toward tumor cells in vitro as well as in a variety of xenograft models of cancer." (PMID 32677994, 2020). "A very recent study has shown that CRISPR-mediated ablation of tumor cells’ CD47 highly increased the whole tumor cells vaccine-induced immunity in hematopoietic and solid tumor models." (PMID 32973401, 2020).
tumor (continued). "CD47 is highly expressed on multiple tumor cell surface membranes involved in regulating macrophage phagocytosis via binding SIRPα to protect host cells from being eliminated." (PMID 33469516, 2020). "This event reduced tumor progression, endowing TAMs with a higher phagocytic capacity, bypassing the CD47 immune checkpoint." (PMID 32823961, 2020). "CD47+ primary tumor cells and CD47+ CTCs were evident in 88.5% and 84.6% of patients, respectively (positivity concordance of 76.9%)." (PMID 32041353, 2020). "Although CD47 can protect normal cells, it renders malignant cells resistant to efferocytosis and promotes tumor progression, suggesting its contradictory role in efferocytosis." (PMID 32346605, 2020). "In summary, pre-clinical data demonstrate that the tumor selectivity of certain anti-CD47 antibodies is based on the relative expression of the anti-phagocytic signal CD47 and pro-phagocytic signals." (PMID 32038992, 2019). "CD47 blockade can effectively reeducate microglia in the GBM tumor microenvironment to unleash the therapeutic potential of tumor cell phagocytosis." (PMID 30602457, 2019). "Several previous studies showed that anti-CD47 targeting was effective in suppressing tumor growth in some human cancer xenograft models." (PMID 31771616, 2019). "CD47 blockade has been shown to potentiate macrophage-mediated phagocytosis of tumor cells in numerous models and is currently in several clinical trials to treat various cancers." (PMID 30770827, 2019). "Other escape mechanisms involve the expression of checkpoint inhibitors such as programmed death ligand 1 (PD-L1) and CD47 which mainly control the activity of tumor-specific T cells and macrophages." (PMID 31921125, 2019). "Anti-CD47 therapy with a CD47 antagonist increased the tumor infiltration of CD8+ T cells in a preclinical model of ESCC." (PMID 31771653, 2019). "Despite the presence of CD47 in the growing tumor, the immune response that now consists of tumor-specific cytotoxic T cells, will prove to be efficient in curbing further growth." (PMID 31882679, 2019). "Accumulating preclinical data indicate that targeting the SIRPα/CD47 axis alone or in combination with existing targeted therapies or immune checkpoint inhibitors enhances tumor rejection." (PMID 31801627, 2019). "Using patient-derived melanoma cells, we recently demonstrated that blockade of CD47 leads to their efficient phagocytosis and suppression of tumor growth and metastases in vivo." (PMID 31568485, 2019). "CD47-SIRPα myeloid checkpoint blockade has been shown to effectively enhance tumor phagocytosis and hence reduce tumor burden." (PMID 30602457, 2019). "Targeting CD47, or interfering with the CD47-SIRPα axis leads to enhanced tumor phagocytosis by macrophages and represents a promising therapeutic strategy to treat CSCs." (PMID 31709180, 2019). "These macrophages are now capable of recognizing and phagocytosing the CD47-null tumor cells and presenting antigens effectively to T cells, leading to the development of a robust downstream immune response." (PMID 31882679, 2019). "Using this mouse model, we found that treatment with anti-CD47 alone resulted in significantly reduced tumor growth compared to the untreated animals." (PMID 31771616, 2019). "In the Panc02 tumor model, we found that anti-CD47 mAb or anti-PD-L1 mAb treatment alone resulted in a decreased tumor growth compared to that of untreated animals; however, no synergistic effect was observed." (PMID 31771616, 2019). "This clinical result is supported by the pre-clinical finding that anti-CD47 antibody can induce a CD8 T-cell specific anti-tumor response through cross-presentation of tumor antigens by macrophages to T cells upon tumor engulfment." (PMID 32038992, 2019). "In a recent study, humanized anti-CD47 antibody, Hu5F9-G4, blocked CD47-SIRPα interactions that halt macrophages from destroying tumor cells." (PMID 30876441, 2019).
tumor (continued). "When using several tumor models syngenically transplanted into immune-competent mice, blocking CD47 promotes massive destruction of tumor cells by a mechanism mainly depending on T lymphocytes activation." (PMID 31540045, 2019). "This suggested that a major portion of CD47 mAb-mediated tumor cell death was a result of M1 macrophage-mediated phagocytosis." (PMID 30674867, 2019). "CD47 is involved in inflammatory response and is recognized as an immune checkpoint for tumor evasion." (PMID 30892634, 2019). "Pre-incubation with anti-CD47 antibody significantly increased engulfment of tumor cells by both IPSDMs (57.8%) and PBDMs (54.0%), compared with controls without CD47 blocking antibody (16.2% and 10.7%) (and data not shown)." (PMID 31189095, 2019). "In contrast, tumor cell phagocytosis by microglia was significantly enhanced upon anti-CD47 treatment (0.9% control versus 8.7% treated, P = 0.0019)." (PMID 30602457, 2019). "The clinical relevance of immune escape by CD47 up-regulation on tumor cells is also reflected by correlation studies: high levels of CD47 expression are associated with a decreased probability of overall survival in GBM." (PMID 30602457, 2019). "The antagonistic anti-CD47 mAb Hu-5F9G4 induces phagocytosis of tumor cells by blocking the CD47-SIRPα interaction." (PMID 31402908, 2019). "A strong positive correlation between enhanced CD47 protein expression and disease progression or tumor stage was established." (PMID 31861233, 2019). "We found increased calreticulin staining on the cell surface of MNNG/HOS tumor cells undergoing doxorubicin or combination treatment compared to PBS‐treated or CD47 mAb‐treated tumor cells (P = 0.0001)." (PMID 31376208, 2019). "We investigated if the anti-tumor effect of CD47 targeting requires both innate and adaptive immunity, by implanting Panc02 cells to C57BL/6 mice." (PMID 31771616, 2019). "Mice were treated with either anti-CD47 mAb or antibody dilution buffer, respectively, and subsequent tumor growth was repeatedly measured by ultrasound." (PMID 30938231, 2019). "After confirming tumor engraftment by bioluminescence imaging, we started treatment with anti-CD47 (250 μg Hu5F9-G4 three times a week) or human IgG control and analyzed the tumor environment after 25 d by flow cytometry." (PMID 30602457, 2019). "On the other hand, CD47 blockade drives the phagocytosis of the tumor and T cell-mediated antitumor immune responses 76-78." (PMID 31754376, 2019). "Tumor phagocytosis activity in the presence of anti-CD47 was next determined on M0-, M1-, and M2-IPSDMs, and we show that M0- and M2-IPSDMs had the highest tumor phagocytosis activity." (PMID 31189095, 2019). "CD47 mAb-treated tumors were significantly smaller compared to control IgG-treated tumors on day 10 of therapy, indicating successful tumor growth inhibition (p = 0.001)." (PMID 30674867, 2019). "Beyond its physiological role, CD47 is overexpressed by tumor cells, induced by oncogenic activation of c-MYC, as an escape strategy from macrophage phagocytosis and is currently under evaluation for therapeutic targeting, with promising results." (PMID 31067629, 2019). "Targeting SIRPα enhanced tumor cell uptake by macrophages and neutrophils at a similar rate as anti-CD47 mAbs." (PMID 31801627, 2019). "To this end, we compared the immune cell populations in the TDLNs of the mice that were tumor-free - responders (CD47−/− 3BD9 R), and those that developed tumors after vaccination - non-responders (CD47−/− 3BD9 NR)." (PMID 31882679, 2019). "CD47 expression, quantified by the IHC H‐score, was significantly stronger in tumor tissues compared with the adjacent non‐tumor tissues (P < 0.0001)." (PMID 30741466, 2019). "Expression of CD47 in tumor cells avoid their recognition and elimination by macrophages, dendritic cells, and T cells and induces epithelial-mesenchymal transition (EMT) through modulation of N-cadherin and E-cadherin." (PMID 31921125, 2019).
tumor (continued). "To better define the subpopulation structure of the tumor-infiltrating immune cells, we computationally pooled the data from the control and the anti-CD47 group representing a total of 22,608 cells." (PMID 31771616, 2019). "The pharmacological inhibition of CD47 restored phagocytosis and killing of tumor cells by macrophages in various preclinical cancer models, resulting in effective anti-tumor immune responses." (PMID 31878087, 2019). "Taken together, we conclude that ferumoxytol-MRI can monitor tumor response to CD47 mAb therapy non-invasively." (PMID 30674867, 2019). "Bioluminescence imaging data showed a significantly decreased tumor burden in mice treated with doxorubicin plus CD47 mAb as compared to mice treated with doxorubicin only (P = 0.01), CD47 mAb only (P = 0.03), or control IgG (P = 0.001)." (PMID 31376208, 2019). "This is important, as monotherapies cannot reach complete tumor regression and future clinical translations will require integration of CD47 mAb therapies with classical chemotherapy." (PMID 31376208, 2019). "In different tumor types, CD47 has been found to be upregulated and represents an independent negative prognostic factor." (PMID 31277366, 2019). "CD47 mAb-treated tumor sections had significantly increased amount of ferumoxytol nanoparticles, which corresponded to ferumoxytol-MRI signals." (PMID 30674867, 2019). "In the CD47−/− 3BD9 tumor microenvironment, there was a substantial increase in IL-2 and IFN-γ, the cytokines primarily associated with T cell health and deemed indispensable for T-reg cell activity and induction." (PMID 31882679, 2019). "The expression level of two functional proteins on macrophages were detected including SIRPα, the ligand protein of CD47, and CD68, one of the markers of tumor-associated macrophages." (PMID 31139022, 2019). "This also suggests that the CD47 depletion from tumor cells had a very specialized effect on the anti-tumor immune response." (PMID 31882679, 2019). "The tumor-bearing mice were treated with anti-CD47 monoclonal antibody and an anti-PD-L1 mAb, alone or in combination." (PMID 31771616, 2019). "Blockage of tumor-derived CD47 has been shown to promote M1 polarization, leading to improved tumor phagocytosis." (PMID 31708781, 2019). "Taken together, this suggests that agents targeting the SIRPα–CD47 innate immune checkpoint induce anti-tumor immunity by bridging innate and adaptive immune responses." (PMID 31801627, 2019). "For instance, the blocking of CD47-SIRPα interaction using anti-CD47 monoclonal antibodies, anti-SIRPα antibodies, or nanobodies, has shown delayed tumor progression." (PMID 31882679, 2019). "We were, overall, able to achieve a comprehensive overview of the changes that occur in the immune system when it is presented with CD47−/− irradiated tumor vaccines." (PMID 31882679, 2019). "In both Panc02 and MPC-83 tumor models, we found that anti-CD47 mAb or anti-PD-L1 mAb treatment alone or in combination increased the proportion of PD-1+CD8+ T lymphocytes in the peripheral blood, spleens, or tumors, when compared to that of untreated animals." (PMID 31771616, 2019). "We showed for the first time that ferumoxytol-enhanced MRI is a reliable biomarker to monitor tumor response and predict outcomes of CD47 mAb immunotherapy." (PMID 30674867, 2019). "Here, we compared the tumor cell phagocytosis ability of IPSDMs and PBDMs in the presence of a blocking CD47 antibody." (PMID 31189095, 2019). "We studied the inducing a tumor suppressive microenvironment through vaccination of genome edited CD47 tumor cells." (PMID 31882679, 2019). "Taken together, these results suggest that CD47 mAb activates M1 macrophages to phagocytose viable cancer cells and that the majority of tumor cell death occurs after phagocytosis." (PMID 30674867, 2019). "Frequencies of CD45+ tumor-infiltrating leukocytes and CD11b+ F4/80+ double-positive (DP) macrophages were significantly higher in anti-CD47-treated mice." (PMID 30938231, 2019).
tumor (continued). "We performed a study to determine how the tumor microenvironment changes after vaccination with genome edited CD47−/− syngeneic tumor cells." (PMID 31882679, 2019). "Some types of tumor cells have co-opted the CD47-SIRPα signaling axis by elevating their CD47 expression to downregulate phagocytosis and avoid innate immune surveillance." (PMID 31276567, 2019). "CD47 is a molecule with an immunoglobulin-like domain that is expressed on tumor cell surface and inhibits macrophage phagocytosis via binding the signal regulatory protein α (SIRPα) on phagocytes." (PMID 30653520, 2019). "Patients with high tumor expression of CD47 had worse OS (HR = 1.673; p = 0.037), compared to those with low CD47 expression." (PMID 31771616, 2019). "Several pre-clinical studies have demonstrated that CD47 blockade in combination with T cell checkpoint inhibitors can enhance anti-tumor activity." (PMID 32038992, 2019). "Masking of CD47 on tumor cells using monoclonal antibody or soluble SIRPα-Fc construct can trigger ADCP of tumor cells by TAMs." (PMID 31805946, 2019). "Humanized MAbs and a SIRPα-Fc decoy receptor targeting CD47 are now in early stages of clinical development based on the compelling body of preclinical results and human tumor expression data." (PMID 31276567, 2019). "Blocking CD47 resulted in significantly reduced tumor volumes and weights after six weeks of treatment." (PMID 30938231, 2019). "Blocking CD47 directly on tumor cells neutralizes the suppressive CD47 signal and activates macrophages through binding of the CD47-targeting agents to the FcγRs." (PMID 31801627, 2019). "M0-IPSDMs showed similar tumor phagocytosis activity compared with M0-PBDMs in the presence of CD47-blocking antibody." (PMID 31189095, 2019). "In brief, these results showed that blocking CD47 by SIRPα-Fc potentiated anti-tumor response of NSCLC to VEGF blockade." (PMID 31829270, 2019). "It has recently been shown that TAX2, a 12 amino-acid peptide stretch of CD47, specifically inhibits the THBS1/CD47 interaction, causing necrosis in various tumour models." (PMID 30850588, 2019). "For example, tumor-specific inactivation of Myc expression was shown to reverse immune evasion by preventing the Myc-induced transcriptional activation of PD-L1 and CD47." (PMID 31289611, 2019). "For instance, an anti-mouse CD47 nanobody significantly increased antibody-dependent phagocytosis of tumor cells by macrophages in vitro." (PMID 31544819, 2019). "When both anti-CD47 mAb and anti-PD-L1 mAb were applied, the inhibition of tumor growth was synergistic compared to either anti-CD47 or anti-PD-L1 alone, as assessed by the tumor volume (p < 0.001; p = 0.006) and weight (p < 0.001; p = 0.005)." (PMID 31771616, 2019). "High levels of tumor-infiltrating CD68+ M, CD163+ M2, and CD47 expression were significantly associated with worse survival." (PMID 31771616, 2019). "To ascertain if TA-MG can act as effector cells upon CD47-SIRPα blockade, we analyzed the frequency of in vivo phagocytized tumor cells 3 wk after anti-CD47 or control treatment by flow cytometry." (PMID 30602457, 2019). "FoxP3 positivity localized in the nuclei of a subset of lymphocytes, and membranous CD47 positivity was seen in tumour cells of 78% of tested cases." (PMID 31358801, 2019). "Interactions between CD47 and SIRPα prevent tumor cells from undergoing phagocytosis, allowing cancer cells to escape immune surveillance." (PMID 31805946, 2019). "We next examined tumor growth by implanting CD47−/− 3BD9 cells in syngeneic immunocompetent C57BL/6 mice." (PMID 31882679, 2019). "We found in our studies that the right cocktail of factors that modulate cytokine release, macrophage activation, and engage tumor-specific antigens can vividly enhance the already positive effects of CD47 as an immunotherapeutic target." (PMID 31882679, 2019).